CTLA4 (cytotoxic T-lymphocyte associated protein 4)
Diseases named in the same sentence as CTLA4 in open-access papers (continued):
Sharing a sentence is not in itself a finding about the gene and the disease.
glioma (continued). "Studies have confirmed that the increased of immune checkpoints such as PD-L1, CTLA-4, TIM-3, and LAG3 in glioma helps tumor immune evasion, leading to T cell dysfunction." (PMID 35309512, 2022). "We investigated the immune checkpoint expression in glioma specimens and uncovered that CD274 (PD-L1), PDCD1, PDCD1LG2, CTLA4, CD276, HAVCR2, and LAG3 were significantly overexpressed in the high DDR score subtype." (PMID 35720326, 2022). "To further validate the pro-tumoral role of LIGHT in glioma, we performed the Pearson correlation test to examine the relationship between LIGHT and immune checkpoint members, including HVEM, CTLA-4, PD-L1, PD-1, TIM3, LAG3, B7-H3, and B3-H4." (PMID 34513918, 2021). "The GASC score was positively correlated with PD-1, PD-L1, PD-L2, TL1A, TIM3, Galactin-9, CTLA-4, CD80, CD86, CD155, LAG3, and CIITA in all glioma population and the HGG population." (PMID 33996602, 2021). "Recruitment of glioma patients for phase I, II, and III trials using the CTLA-4 inhibitor ipilimumab (a mAb) in combination with a PD-1 inhibitor is ongoing (NCT04323046, NCT04396860, NCT04003649, NCT03233152, NCT04145115)." (PMID 34298735, 2021). "Studies have confirmed that the increased immune checkpoints such as PD-L1, CTLA-4, TIM-3, and LAG3 in glioma help tumor immune evasion, leading to T-cell dysfunction." (PMID 35211508, 2021). "Intriguingly, other immunological indices including PD‐1, CTLA4, and IDO‐1, which are closely related to glioma progression, were also found to be abundantly expressed in the high‐risk score group." (PMID 33969928, 2021). "We found that CTLA-4 tended to be expressed at higher level in higher grade gliomas, IDH-wild-type gliomas, and mesenchymal-subtype gliomas." (PMID 31911758, 2020). "A triple combination of anti-CTLA-4, anti-PD-1 and a recombinant oncolytic HSV expressing mouse IL-12 (G47Δ-mIL12) cured most mice in two glioma models." (PMID 33154756, 2020). "The frequency at which of CD8+ T cells expressed several of these immune targets, such as PD-1, LAG-3, CTLA-4, and CD39, was higher in the glioma microenvironment than in the PBMCs from patients with GBM and healthy donors." (PMID 32721947, 2020). "In our study, we found that CTLA-4 was significantly correlated with PD-1, CD40, and ICOS in patients with glioma and glioblastoma." (PMID 31911758, 2020). "In newly diagnosed grade 3 gliomas, the descending frequency of expression was A2aR > PD-1 > CD39 > CD73 > TIGIT > LAG-3 > BLTA > CD160 > CTLA-4 > KIR > TIM3 on CD8+ T cells." (PMID 32721947, 2020). "In glioma patients, the accumulation of CD4+/CD8+ T cells and T regulatory cells (Tregs) that express high levels of CTLA-4 and PD-1, or the high expression of PD-L1 in glioma cells correlates with WHO high grade and short survival." (PMID 30857299, 2019). "In glioma patients the accumulation of CD4+/CD8+ T cells and Treg expressing high levels of CTLA-4 and PD-1, or the high expression of PD-L1 in glioma cells correlates with WHO high grade and short survival." (PMID 30406030, 2018). "Consistently with their functions, PD-1/PD-L1, CTLA-4, and IDO are highly expressed in glioma microenvironment." (PMID 27756892, 2017). "When mAbs for CTLA-4 and PD-L1, together with the IDO inhibitor, 1-MT, were administered to mice bearing glioma, Treg levels in glioma microenvironment decreased significantly, and the combination was more effective than the single agent." (PMID 27756892, 2017). "Similar to PD-1, CTLA-4, and IDO, these immune checkpoints inhibit lymphocyte activity and/or induce lymphocyte anergy, and thus are ideal targets for glioma immunotherapy." (PMID 27756892, 2017). "Blockade of the CTLA-4 and PD1 immune checkpoints represents a potentially important anti-glioma strategy that has proven effective in preclinical models of glioma and has warranted exploration in ongoing clinical trials." (PMID 27178315, 2016).
glioma (continued). "A triple combination of RT, anti-CTLA-4, and anti-CD137 further improved survival in this pre-clinical model through a CD4+ T-cell-dependent manner and created a glioma-specific protective memory response." (PMID 26500646, 2015). "CD4+FoxP3+ Tregs in gliomas have been shown to express a variety of immuno-regulatory molecules, such as CD25, CTLA-4, GITR (glucocorticoid-induced TNFR family related gene), and CXCR4 at high levels." (PMID 24202450, 2013). "Signature scores of immune checkpoints, including CTLA4, LAG3, PDCD1, PD-L1, PD-L2 and TIGIT as well as the top five marker genes within each TAM subset were calculated using RNA-seq data from TCGA low grade glioma patients." (PMID 38515213, 2024). "Specifically, we found that, as IGFBP5 levels increased, the expression of the seven immune checkpoint genes (BTLA, CD274, CTLA4, HAVCR2, LAG3, PDCD1, and PDCD1LG2) were increased and a large positive correlation was observed between IGFBP5 and these immune checkpoints in glioma." (PMID 38164271, 2024). "Neither anti-CTLA-4 antibody alone nor in combination with anti-PD-1 antibody yielded long-term survival benefits for glioma patients." (PMID 37354488, 2023). "In addition, CTLA-4 and PD-1 expression levels were low in brain regulatory T cells (Tregs) of glioma bearing mice, indicating that alternative (perhaps glioma-specific) immune checkpoints may play an essential role in immunosuppression of the glioma microenvironment." (PMID 37845206, 2023). "In addition to CTLA4, PD-1, and LAG3, other immunosuppression-related genes, like IGFBP2 and LGALS1 are highly expressed in patients with glioma." (PMID 37399661, 2023). "Consequently, our PRLs had comparable performance in predicting the glioma response to anti-PD1 and anti-CTLA4 treatments, indicating that stratification based on PRLs has the possible to recognize ICB reactors." (PMID 36917093, 2023). "Moreover, REST expression was positively associated with immune cell infiltration and biomarkers of immune cells in glioma, as well as the immune checkpoints PD1, PD-L1, and CTLA-4, indicating its impact on tumor immunity." (PMID 36810892, 2023). "Single anti-CTLA-4 therapy has neither improved symptom-free survival in GL261 glioma mouse model, nor enhanced the costimulatory capacity of antigen-presenting cells (APCs)." (PMID 37444531, 2023). "Indeed, the expression of A3C displayed positive correlations with CD274, PDCD1, PDCD1LG2, SIGLEC15, CTLA4, HAVCR2, and GZMB in glioma (P < 0.05)." (PMID 37809064, 2023). "The results showed that the upregulation of PLEKHA4 expression was significantly related to PD-1/PD-L1, CTLA4, and TIM-3 in glioma, indicating that targeting PLEKHA4 may improve immunotherapy in glioma." (PMID 36714030, 2023). "Unfortunately, anti-PD-1 and anti-CTLA4 monotherapy, although an important step in the right direction, was not as effective as it was hoped to be for gliomas." (PMID 36276141, 2022). "Correspondingly, it showed that CD101 expression could potentially interact with numerous immune-relevant genes, including CD276, CD274, CD80, CTLA4, and PDCD1, implying an immunoregulatory role of CD101 in the glioma immune microenvironment." (PMID 35350788, 2022). "By analyzing the main signaling pathways that induce the EMT phenotype, we found that TGF-β was the most important one in gliomas, and TGFB1/TGFBR1 showed stronger immunosuppressive properties than PD-L1 and CTLA-4, especially in inducing an increase in CD8+ T cytopenia and M2 macrophages." (PMID 36778912, 2022). "Moreover, glioma cells express increased levels of immunosuppressive factors such as PD-L1, TIGIT, CD96, and CTLA-4, which negatively regulate presentation of antigens and T-cell responses." (PMID 35281049, 2022).
glioma (continued). "Except for PD-1, CTLA4, and LAG3, the expression of other immunosuppression-related genes, such as LGALS1 and IGFBP2, is higher in glioma patients, and blocking the expression of immunosuppression-related genes can reshape the immunosuppressive microenvironment." (PMID 35928818, 2022). "Most individuals with poor glioma are not candidates for immunotherapy (Immunologic checkpoint, inhibiting [PD-1/L1 and CTLA4])." (PMID 35903107, 2022). "Recently, studies in glioma xenograft models revealed that systemic administration of monoclonal antibody (9H10) to target CTLA-4 served prolonged survival in 80% of treated mice without exhibiting allergic encephalomyelitis." (PMID 35392976, 2022). "Finally, to investigate the predictive performance of HAUS1 based on the infiltration levels of immune cells in glioma, ROC curves were generated to compare the AUC values of HAUS1, PD-L1, CTLA-4, and Siglec15." (PMID 35865089, 2022). "PD-1 and CTLA-4 have been successfully targeted in other indications without much success in the glioma setting." (PMID 33535555, 2021). "Another phase I trial is looking at a different combination of ICIs, treating recurrent glioma patients with durvalumab and an anti-CTLA-4 antibody (NCT02794883); however, no updates have been given." (PMID 34298615, 2021). "Clinical trials have recently begun assessing anti-CTLA-4 therapies in treating gliomas (NCT02311920, NCT02829931), though no trials have been completed with glioma patients to date." (PMID 34298615, 2021). "Higher CTLA-4 expression was found in patients with higher grade, isocitrate dehydrogenase (IDH)-wild-type, and mesenchymal-molecular subtype gliomas than in patients with lower grade, IDH-mutant, and other molecular subtype gliomas." (PMID 31911758, 2020). "However, the key immunosuppressive factor CTLA-4 was confirmed elevated in EGFR-MUT cases, which indicating a possible existence of Treg cells in lower-grade glioma context." (PMID 31801484, 2019). "Similarly, anti-CTLA-4 antibodies in conjunction with IL-12, which promotes survival of T cells, was effective against GL261 glioma cells." (PMID 30366424, 2018). "We anticipate that glioma tissues with relatively more MBD3 would respond better to therapeutic vaccination and immune-checkpoint-blockade agents (e.g., PD-1/PD-1L inhibitors and CTLA-4 blockade)." (PMID 27835581, 2016). "Targeting cytotoxic T-lymphocyte antigen 4 (CTLA-4), which modulates early stages of T-lymphocyte activation, has proved useful in reversing immunoresistance in gliomas, as it has in non-CNS tumors." (PMID 26217588, 2015). "We hypothesized that radiation therapy followed by 4-1BB activation and CTLA-4 blockade produces an effective and durable anti-tumor response against intracranial GL261 gliomas." (PMID 25013914, 2014). "Furthermore, CD96 shows strong concordance with other immune checkpoint proteins such as TIGIT, CD226, and CRTAM, as well as established markers including PD-L1, CTLA-4, TIM-3, and STAT3, suggesting its potential for synergistic antitumoral effects in glioma immunotherapy​​." (PMID 38342925, 2024). "Statistical analysis based on clinical data has shown that CTLA-4 expression is higher in patients with higher grade, isocitrate dehydrogenase (IDH)-wild-type and mesenchymal-molecular subtype gliomas compared to patients with lower grade, IDH-mutant and other molecular subtype gliomas." (PMID 38660136, 2024). "By conducting Pearson correlation analysis on glioma samples from the CGGA and TCGA databases, it was discovered that the expression of SOCS1 is significantly positively correlated with several known inhibitory immune checkpoints, including HVEM, TIM-3, PD-1, PDCD2, TIGIT, CD200R1, CTLA4, and CD47." (PMID 39654174, 2024). "This may also partly explain there have been no breakthroughs in targeting CTLA-4 and anti-PD-1 in the treatment of glioma." (PMID 36882457, 2023).
glioma (continued). "Our research found that the expression levels of six immune checkpoint inhibitors (B7-H3, CTLA4, LAG3, PD-1, PD-L1, and TIM3) were increased with the increase in MELK expression, and significant positive correlations have been found between MELK and these immune checkpoints in glioma." (PMID 36353126, 2022). "Finally, the AUC values of Siglec15, CTLA-4, PD-L1 and TP53I13 were compared, and the ROC curve was calculated to evaluate whether TP53I13 could predict the immune infiltration of glioma." (PMID 36275718, 2022). "The results implied the significant clinical response and therapeutic advantages to anti-PD-1 immunotherapy (high IPS) in glioma patients with high PSscore compared to those with low PSscore, but the response to anti-CTLA-4 immunotherapy without significant differences between these two groups." (PMID 35274175, 2022). "Therefore, BTN2/3 subfamily expression could possibly promote the development of pan-glioma by enhancing PD1 expression interacting with PDL1 and inhibiting CD4 and CD8 T-cell differentiation by upregulating CTLA4." (PMID 36033440, 2022). "Studies have shown that the upregulation of immune checkpoints such as PD-L1, CTLA-4, TIM-3, and LAG3 in glioma helps tumor immune evasion, leading to T cell dysfunction, suggesting that METTL7B may promote tumor immune evasion by upregulating the expression of immune checkpoints." (PMID 33996568, 2021). "However, the expression of CTLA-4 in glioma and the effects of CTLA-4 on prognosis in patients with glioma have not yet been examined." (PMID 31911758, 2020). "Further, Tim-3 and other exhausting immune molecules (LAG-3, PD-1, CTLA4, CD244, and PD-1) exhibited significantly different expression profiles between normal brain tissues and GBM tissues according to the TCGA database, indicating their potential correlation with glioma progression." (PMID 33041828, 2020). "However, PD-1, CTLA-4, or VEGF blockade exhibited only poor outcome in glioma patients." (PMID 33604291, 2020). "In response to DC vaccines, an innovative therapeutic method for patients with glioma, the down-regulation of CTLA-4 on peripheral blood lymphocyte closely correlates with good prognosis in glioma patients, further supporting the significance of CTLA-4 in regulating anti-tumor immune responses." (PMID 27756892, 2017). "In addition to PD-1, CTLA-4, and IDO, other immune checkpoints are also involved in the occurrence and development of glioma, including T cell membrane protein-3 (TIM-3; also known as HAVcr2), killer inhibitory receptors (KIR), and V-domain Ig-containing suppressor of T cell activation (VISTA)." (PMID 27756892, 2017). "Furthermore, a combination of RT and CTLA-4 mAb treatment prolonged the OS in an orthotopic GL261 glioma model, whereas CTLA-4 mAb alone was not able to extend the survival in comparison to untreated controls." (PMID 26500646, 2015). "Correlation analysis showed that ZBTB42 was positively related to PD1, PD-L1, PD-L2, CTLA4, TIM3, and LAG3 in LGG and positively related to PD-L1, PD-L2, SIRPA in GBM, suggesting that the high expression of ZBTB42 may promote glioma progression via immune suppression microenvironment." (PMID 36762114, 2023). "However, more detailed and comprehensive reports of CTLA-4 expression in glioma is lacking." (PMID 31911758, 2020). "Additionally, when used in combination with a glioma vaccine of irradiated glioma cell lines expressing granulocyte macrophage-colony stimulating factor (GM-CSF), there was improved survival and increased levels of IFN-γ production compared to treatment with CTLA-4 blocking mAb alone." (PMID 24202450, 2013). "We found that in patients with glioma, B7‐H3, LAG3 and TIM3 were significantly raised, while the expression of PD‐L1, BTLA, TIGIT, PD‐1 and CTLA4 did not seem to be significantly different from those of normal individuals." (PMID 35668574, 2023).
glioma (continued). "It has been shown that the majority of glioma patients do not respond to blockade of the usual immune checkpoint pathways, such as programmed death receptor-1 (PD1), its ligand (PD-L1), and cytotoxic T-lymphocyte antigen 4 (CTLA-4)." (PMID 37047660, 2023). "The difference in CTLA-4 expression between grade II and grade III gliomas was not significant." (PMID 31911758, 2020). "In this study, some important glioma-related genes were not differentially expressed in PDGFRA-overexpressing canine gliomas, including HIF1-α, CTLA4, DLL3, and TNFRSF12A, important mediators of angiogenesis, immune evasion, self-renewal, and invasion in the tumor microenvironment." (PMID 29352201, 2018). "Combination immunotherapies have also been tested as a treatment in murine models of glioma: the combination of GVAX followed by CTLA-4 blockade resulted in 50% long-term survival in a murine model of intracranial glioma, whereas CTLA-4 blockade alone did not improve survival in established tumors." (PMID 25013914, 2014). "Moreover, co-administration of anti-CTLA-4 antibody and Treg depletion was used to reverse the tumor immune tolerance, further strengthened CD4+ and CD8+ effector T cells, and resulted in complete glioma eradication without autoimmunity." (PMID 27756892, 2017).